AKT2 (AKT serine/threonine kinase 2)
Description:
Serine/threonine kinase closely related to AKT1 and AKT3. All 3 enzymes, AKT1, AKT2 and AKT3, are collectively known as AKT kinase. AKT regulates many processes including metabolism, proliferation, cell survival, growth and angiogenesis, through the phosphorylation of a range of downstream substrates. Over 100 substrates have been reported so far, although for most of them, the precise AKT kinase catalyzing the reaction was not specified. AKT regulates glucose uptake by mediating insulin-induced translocation of the SLC2A4/GLUT4 glucose transporter to the cell surface. Phosphorylation of PTPN1 at 'Ser-50' negatively modulates its phosphatase activity preventing dephosphorylation of the insulin receptor and the attenuation of insulin signaling. Phosphorylation of TBC1D4 triggers the binding of this effector to inhibitory 14-3-3 proteins, which is required for insulin-stimulated glucose transport. AKT also regulates the storage of glucose in the form of glycogen by phosphorylating GSK3A at 'Ser-21' and GSK3B at 'Ser-9', resulting in inhibition of its kinase activity. Phosphorylation of GSK3 isoforms by AKT is also thought to be one mechanism by which cell proliferation is driven. AKT also regulates cell survival via the phosphorylation of MAP3K5 (apoptosis signal-related kinase). Phosphorylation of 'Ser-83' decreases MAP3K5 kinase activity stimulated by oxidative stress and thereby prevents apoptosis. AKT mediates insulin-stimulated protein synthesis by phosphorylating TSC2 at 'Ser-939' and 'Thr-1462', thereby activating mTORC1 signaling and leading to both phosphorylation of 4E-BP1 and in activation of RPS6KB1. AKT is involved in the phosphorylation of members of the FOXO factors (Forkhead family of transcription factors), leading to binding of 14-3-3 proteins and cytoplasmic localization. In particular, FOXO1 is phosphorylated at 'Thr-24', 'Ser-256' and 'Ser-319'. FOXO3 and FOXO4 are phosphorylated on equivalent sites. AKT has an important role in the regulation of NF-kappa-B-dependent gene transcription and positively regulates the activity of CREB1 (cyclic AMP (cAMP)-response element binding protein). The phosphorylation of CREB1 induces the binding of accessory proteins that are necessary for the transcription of pro-survival genes such as BCL2 and MCL1. AKT phosphorylates 'Ser-454' on ATP citrate lyase (ACLY), thereby potentially regulating ACLY activity and fatty acid synthesis. Activates the 3B isoform of cyclic nucleotide phosphodiesterase (PDE3B) via phosphorylation of 'Ser-273', resulting in reduced cyclic AMP levels and inhibition of lipolysis. Phosphorylates PIKFYVE on 'Ser-318', which results in increased PI(3)P-5 activity. The Rho GTPase-activating protein DLC1 is another substrate and its phosphorylation is implicated in the regulation cell proliferation and cell growth. AKT plays a role as key modulator of the AKT-mTOR signaling pathway controlling the tempo of the process of newborn neurons integration during adult neurogenesis, including correct neuron positioning, dendritic development and synapse formation. Signals downstream of phosphatidylinositol 3-kinase (PI(3)K) to mediate the effects of various growth factors such as platelet-derived growth factor (PDGF), epidermal growth factor (EGF), insulin and insulin-like growth factor 1 (IGF1). AKT mediates the antiapoptotic effects of IGF1. Essential for the SPATA13-mediated regulation of cell migration and adhesion assembly and disassembly. May be involved in the regulation of the placental development. In response to lysophosphatidic acid stimulation, inhibits the ciliogenesis cascade. In this context, phosphorylates WDR44, hence stabilizing its interaction with Rab11 and preventing the formation of the ciliogenic Rab11-FIP3-RAB3IP complex. Also phosphorylates RAB3IP/Rabin8, thus may affect RAB3IP guanine nucleotide exchange factor (GEF) activity toward Rab8, which is important for cilia growth. Phosphorylates PKP1, facilitating its interaction with YWHAG and translocation to the nucleus, ultimately resulting in a reduction in keratinocyte intercellular adhesion (By similarity). Phosphorylation of PKP1 increases PKP1 protein stability, translocation to the cytoplasm away from desmosome plaques and PKP1-driven cap-dependent translation. Several AKT2-specific substrates have been identified, including ANKRD2, C2CD5, CLK2 and PITX2. May play a role in myoblast differentiation. In this context, may act through PITX2 phosphorylation. Unphosphorylated PITX2 associates with an ELAVL1/HuR-containing complex, which stabilizes CCND1 cyclin mRNA, ensuring cell proliferation. Phosphorylation by AKT2 impairs this association, leading to CCND1 mRNA destabilization and progression towards differentiation (By similarity). Also involved in the negative regulation of myogenesis in response to stress conditions. In this context, acts by phosphorylating ANKRD2 (By similarity). May also be a key regulator of glucose uptake. Regulates insulin-stimulated glucose transport by the increase of glucose transporter GLUT4 translocation from intracellular stores to the plasma membrane. In this context, acts by phosphorylating C2CD5/CDP138 on 'Ser-197' in insulin-stimulated adipocytes (By similarity). Through the phosphorylation of CLK2 on 'Thr-343', involved in insulin-regulated suppression of hepatic gluconeogenesis (By similarity).
Synonyms: PKBβ; HIHGHH; PKBB; PKBBETA; PRKBB; RAC-BETA
Tractability: Small molecule: a drug acting on it is in phase 2 or 3 trials; a structure with a bound ligand is known; a high-quality ligand is known; it has a high-quality binding pocket; it belongs to a druggable protein family. Antibody: its Gene Ontology location is reachable by antibodies, with high confidence; UniProt places it where antibodies can reach, with medium confidence. PROTAC: it is named in the literature on targeted protein degradation; UniProt records ubiquitination sites on it; ubiquitination databases record sites on it; its protein half-life has been measured; a small molecule that binds it is known.
Target class: AGC protein kinase AKT family; Enzyme; Protein Kinase; AGC protein kinase group; Kinase
Chemical probes: BAY1125976 (high quality), Borussertib (high quality), GSK619487A, INY-03-041 (high quality), PD080927, PD080945, PD082373, PD134375, PD134376, capivasertib (high quality)
Safety:
Unwanted effects reported when the protein is acted on. In parentheses: how it was acted on, where the effect was seen, and who reports it.
Increased, Liver Steatosis (activation; source: AOP-Wiki)
heart disease (cardiovascular system; source: Force et al. (2011))
Gene: Protein-coding gene on chromosome 19 (40,230,317 to 40,285,536, reverse strand). Ensembl gene ENSG00000105221.
Subcellular location: Cytoplasm; Nucleus; Cell membrane; Early endosome
Subcellular location (Human Protein Atlas): Cytosol; Vesicles; Nucleoplasm
Pathways (Reactome):
Signal Transduction: AKT phosphorylates targets in the cytosol; AKT phosphorylates targets in the nucleus; Activation of AKT2; Deactivation of the beta-catenin transactivating complex; Downregulation of ERBB2:ERBB3 signaling; Estrogen-dependent nuclear events downstream of ESR-membrane signaling; G beta:gamma signalling through PI3Kgamma; Inhibition of TSC complex formation by AKT (PKB); MTOR signalling; Negative regulation of the PI3K/AKT network; PDE3B signalling; PIP3 activates AKT signaling; Regulation of PTEN stability and activity; VEGFR2 mediated vascular permeability
Gene expression (Transcription): RUNX2 regulates genes involved in cell migration; Regulation of localization of FOXO transcription factors
Immune System: CD28 dependent PI3K/Akt signaling; Co-inhibition by CTLA4; FLT3 Signaling
Cell Cycle: Cyclin A:Cdk2-associated events at S phase entry; Cyclin E associated events during G1/S transition
Developmental Biology: AKT-mediated inactivation of FOXO1A; Regulation of MITF-M-dependent genes involved in pigmentation
Disease: Constitutive Signaling by AKT1 E17K in Cancer; SARS-CoV-2 targets host intracellular signalling and regulatory pathways
Vesicle-mediated transport: RAB GEFs exchange GTP for GDP on RABs; Translocation of SLC2A4 (GLUT4) to the plasma membrane
Cellular responses to stimuli: KEAP1-NFE2L2 pathway
Programmed Cell Death: Activation of BAD and translocation to mitochondria
Gene Ontology:
Molecular function: ATP binding; molecular function activator activity; protein binding; protein serine/threonine kinase activity; protein kinase activity; protein serine kinase activity
Biological process: cellular response to insulin stimulus; insulin receptor signaling pathway; negative regulation of long-chain fatty acid import across plasma membrane; positive regulation of cap-dependent translational initiation; positive regulation of cell migration; positive regulation of cell motility; positive regulation of D-glucose import; positive regulation of fatty acid beta-oxidation; positive regulation of glucose metabolic process; positive regulation of glycogen biosynthetic process; protein stabilization; fat cell differentiation; intracellular signal transduction; mammary gland epithelial cell differentiation; negative regulation of apoptotic process; positive regulation of blood vessel endothelial cell migration; positive regulation of protein targeting to membrane; protein modification process; regulation of cell cycle; regulation of cell migration; signal transduction; negative regulation of PERK-mediated unfolded protein response
Cellular component: cytoplasm; cytosol; nucleoplasm; nucleus; cell cortex; early endosome; plasma membrane; ruffle membrane
Genetic constraint (gnomAD): Loss-of-function variants: 16 observed, 61.11 expected, observed/expected ratio (o/e) 0.26, 90% interval 0.18 to 0.4. The upper end of that interval is the gene's LOEUF score, 0.4, which puts it in group 1 of 6, group 1 being the genes least tolerant of losing a copy. Missense variants: 438 observed, 683.23 expected, observed/expected ratio (o/e) 0.64, 90% interval 0.59 to 0.69. Synonymous variants: 253 observed, 263.98 expected, observed/expected ratio (o/e) 0.96, 90% interval 0.86 to 1.06.
Gene-disease validity (ClinGen):
ClinGen rates the evidence that AKT2 causes each of these diseases.
hypoinsulinemic hypoglycemia and body hemihypertrophy (autosomal dominant): Definitive.
AKT2-related familial partial lipodystrophy (autosomal dominant): Limited.
Cancer hallmarks: invasion and metastasis (promotes); proliferative signalling (promotes); invasion and metastasis (suppresses); change of cellular energetics (promotes); escaping programmed cell death (promotes)
Homologues: Orthologues: chimpanzee AKT2 (99% identical), rat Akt2 (98% identical), guinea pig AKT2 (98% identical), mouse Akt2 (98% identical), pig AKT2 (96% identical), tropical clawed frog akt2 (88% identical), zebrafish akt2 (86% identical), dog AKT2 (85% identical), macaque AKT2 (84% identical), zebrafish akt2l (81% identical), rabbit AKT2 (76% identical). Paralogues in human: AKT1 (81% identical), AKT3 (77% identical), PRKCQ (40% identical), PRKCD (38% identical), PDPK1 (29% identical).
Diseases named in the same sentence as AKT2 in open-access papers:
AKT2 is named in the same sentence as 251 diseases in open-access papers, as found by Europe PMC text mining. Sharing a sentence is not in itself a finding about the gene and the disease. The quoted sentences say what the papers report.
breast cancer (149 papers, 2005 to 2025). A primary or metastatic malignant neoplasm involving the breast. "Both AKT1 and AKT2 have been implicated in breast cancer previously, with some mixed results regarding their specific function." (PMID 39057065, 2024). "In contrast, systematic Akt2 loss promoted breast cancer development but impairs breast cancer migration and metastasis, indicating distinct functions of Akt isoforms in breast cancer development, breast cancer migration and metastasis." (PMID 36180910, 2022). "We found that frequency of PIK3CA H1047R mutation was 14.3% using Sanger sequencing in canine mammary tumors, and downstream molecules Akt2, p-Akt, and PTEN were dysregulated in mammary tumors when compared to normal mammary gland." (PMID 34359206, 2021). "Akt2 was also associated with worse clinical outcome and was considered a worthwhile target for breast cancer therapy." (PMID 34298660, 2021). "According to earlier studies, mutations in the Akt2 isoform are quite rare whilst amplifications in the isoform have been detected in 16% of pancreatic cancers; 16% of uterine cancers; 13% of breast cancers; and 5–10% of ovarian, lung, and bladder cancers." (PMID 33916378, 2021). "For example, in a mouse breast cancer model induced by polyoma middle T (PyMT) or ErbB2/Neu, loss of Akt1 significantly delayed tumor induction while loss of Akt2 accelerated this endpoint." (PMID 33110146, 2020). "Accordingly, AKT1 is mutated and AKT2 is amplified in some cases of breast cancer and AKT isoforms are associated with overall survival and therapy response in an isoform-specific manner." (PMID 31752925, 2019). "Comparison of the AKT1 E17K mutation and the mutation of PIK3CA displays enhanced AKT1 activity in the AKT1 mutation, but elevated activity of AKT1 and AKT2 in the PIK3CA mutated breast cancer cells." (PMID 31752925, 2019). "The purpose of this study was to elucidate the mechanisms associated with the specific effects of AKT1 and AKT2 isoforms in breast cancer progression." (PMID 28287129, 2017). "AKT2 silencing had a similar effect on PTEN-deficient breast cancer and glioblastoma cell models, whereby AKT2 knockdown caused regression of 3D spheroid growth comparable to prostate cancer models." (PMID 28082369, 2017). "In the mammary tumor mouse model MTB-IGF-IR loss of Akt1 or Akt2 delays mammary tumor onset and suppresses growth." (PMID 27533079, 2016). "It is also worth noting that an analogous E17K mutation has been identified in AKT2 in one breast cancer patient and in AKT3 in melanomas." (PMID 27004402, 2016). "It is also important to note that the E17K somatic mutation has also been identified in AKT2 in breast cancer, albeit at lower frequency, and also in AKT3 in human melanoma." (PMID 27004402, 2016). "AKT2 has been shown to be linked to aggression and drug resistance in a variety of human cancers, including ovarian cancer, breast cancer, endometrial cancer, and malignant gliomas." (PMID 25951903, 2015). "Although loss of Akt1 or Akt2 significantly inhibited mammary tumor onset and growth rates the effects were less dramatic than anticipated." (PMID 23919516, 2013). "Despite the complete loss of Akt1 or Akt2, the level of total phosphorylated Akt remained largely unaffected in the mammary tumors suggesting that loss of one Akt isoform is compensated by enhanced activation of the remaining Akt isoforms." (PMID 23919516, 2013). "Although loss of Akt1 or Akt2 significantly inhibited mammary tumor onset and growth rates these effects were very modest." (PMID 23919516, 2013). "A study in 280 postmenopausal Swedish women with breast cancer indicated that expression of pAkt was significantly associated with both Akt1 and Akt2 staining; however, the correlation was stronger for Akt1 than for Akt2." (PMID 18184439, 2008).
breast cancer (continued). "AKT2 inhibition has been linked to decreased mesenchymal stem cell, breast cancer, and lung cancer cell migration, therefore we may anticipate that increased viscous relaxation rate would correlate with decreased migratory capacity." (PMID 41028875, 2025). "AKT1 and AKT2 mutations activate Akt signaling in HR+/luminal breast cancer." (PMID 33435254, 2021). "Akt2 on the other hand was shown to interact with Prohibitin 2/Repressor of Estrogctivator (PHB2/REA) which has been implicated in transcriptional repression of myogenesis in estrogen-dependent cancers like breast cancer." (PMID 34298660, 2021). "However, in breast cancer models, loss of Akt2 inhibited, while loss of Akt1 accelerated, cell motility and metastasis in both in vitro and mouse breast cancer models." (PMID 33110146, 2020). "Knockdown of AKT2 in PTEN-deficient breast cancer cells reduces 3D spheroid growth." (PMID 28082369, 2017). "Thus, AKT2 can also cause hormone-independency in breast cancer." (PMID 31752925, 2019). "Here, we demonstrated PIPP/PTEN co-depletion further enhanced AKT1 and AKT2 activation in response to growth factor simulation of breast cancer cell lines over single knockdown of either PI-phosphatase." (PMID 41408399, 2025). "Of the three AKT isoforms (AKT1, AKT2 and AKT3), AKT1 and AKT2 are the most prominently associated with human breast cancer initiation and progression." (PMID 41408399, 2025). "For example, breast cancer cell migration and invasion are promoted by Akt2 but suppressed by Akt1, both in vitro and in vivo." (PMID 38291468, 2024). "It is noteworthy that AKT2 is known to control other cancer progression biologies such as epithelial-to-mesenchymal transformation in breast cancer, breast cancer stem cell self-renewal, and lung cancer invasiveness." (PMID 37875657, 2024). "In untransformed fibroblasts, AKT1 promotes migration, and AKT2 has anti-migratory effects, whereas in breast cancer cell lines, the opposite holds true." (PMID 39614261, 2024). "miR-615 was initially found to inhibit cell proliferation in human breast cancer cells by suppressing protein kinase B beta (AKT2) expression." (PMID 38257818, 2024). "As our garlic extract-modified cell events variously correlated with Akt signaling, we explored the Akt status in TNBC cells, focusing on Akt1 and Akt2, which, in breast cancer, mainly regulate cell growth and invasion/metastasis, respectively." (PMID 38786044, 2024). "In 2007, Cheng and co-workers demonstrated that Twist-1 activates AKT2 in breast cancer cells inducing increased invasion, migration and improved resistance to paclitaxel." (PMID 37047018, 2023). "The PI3K/Akt2 signaling pathway is frequently dysregulated in breast cancer and plays a significant role in breast cancer development and progression." (PMID 38145160, 2023). "The Akt family includes three members (Akt1, Akt2 and Akt3) that play distinct roles in breast cancer malignancy, being Akt1 correlated with proliferation of tumor cells and the other two isozymes variously involved in invasion/metastasis." (PMID 35743776, 2022). "As it is known that, in breast cancer, Akt2 is regulated by various miRNAs, including miR-615 and miR-29b, we explored their possible involvement in the mechanism by which Vav1 affects this Akt isoform." (PMID 35743776, 2022). "Silencing of Vav1 resulted in the increased expression in Akt1 in ER+ cells and in the up-modulation of Akt2 in ER- breast tumor cells, including those with a triple negative phenotype, still representing the most aggressive breast cancer." (PMID 35743776, 2022). "In particular, homologs AKT1, AKT2, ERBB2, FGFR2, and PIK3CA in CGC play important roles in breast cancer progression, mediating breast cancer risk, corresponding to the driver candidates RPS6KA1, SGK1, PTK2, IGF1R, PIK3CB, and PRKDC predicted by DriverMP." (PMID 38091511, 2022).